IL17A (interleukin 17A)
Diseases named in the same sentence as IL17A in open-access papers (continued):
Sharing a sentence is not in itself a finding about the gene and the disease.
schistosomiasis (40 papers, 2009 to 2025). An infectious disease caused by parasitic trematodes of the genus Schistosoma that colonize human blood vessels and release eggs that can cause granulomatous reactions leading to acute (swimmer's itch or acute schistosomiasis syndrome) or chronic disease. "In schistosomiasis, IL-17A stimulates a pathogenic inflammatory response that can be alleviated with antibodies to IL-17A." (PMID 40821838, 2025). "According to previous studies, Th17 cells might play an essential role in the immunopathology in the liver and the formation of egg granulomas, and the development of severe schistosomiasis in mice is associated with high levels of IL-17A." (PMID 33628844, 2021). "The cytokine levels of TNF-α, IFN-γ, IL-6, IL-4, IL-5, IL-10, IL-13, and IL-17A in the sera of acute phase schistosomiasis were all significantly increased in the IUT and VEH groups compared with the UI group." (PMID 30258438, 2018). "The data presented here of Luminex analysis displayed markedly correlation between the level of IL-21 or IL-17A in serum and disease severity of schistosomiasis." (PMID 29192177, 2017). "In addition, IL-17A was hardly detected in any of the infection groups, which would be more indicative of chronic inflammatory processes or, in schistosomiasis, be more indicative of severe liver pathology." (PMID 30619332, 2018). "In summary, these findings might suggest thatIL-21 and IL-17A contribute to driving fibrogenesis in schistosomiasis." (PMID 29192177, 2017). "However, during the chronic phase of schistosomiasis, the levels of TNF-α, IFN-γ, IL-6, IL-4, IL-10, and IL-17A remained increased in the IUT and VEH groups." (PMID 30258438, 2018).
glomerulonephritis (39 papers, 2012 to 2025). A renal disorder characterized by damage in the glomeruli. "In necrotic glomerulonephritis, IL-17A deficiency leads to impaired neutrophil recruitment to the glomerulus, which, in turn, downregulates MPO and improves glomerulonephritis." (PMID 37920459, 2023). "The role of IL- 17A has been examined using IL-17A-deficient mice in anti-MPO glomerulonephritis." (PMID 25964886, 2015). "The previous studies on the IL‐17 signalling pathway have indicated that metabolic inflammation‐associated IL‐17A leads to MASH53 and that the IL‐17 signalling pathways are a potential therapeutic target for rapidly progressive glomerulonephritis." (PMID 38429902, 2024). "Previous studies on patients with LN showed abnormal levels of IL-17A both in serum and urine; importantly, serum IL-17A levels heralded major kidney damage in patients with class IV or V glomerulonephritis, in keeping with our data." (PMID 37834330, 2023). "Recently, the role of Th17 cells producing proinflammatory interleukin 17A (IL-17A) was established in the pathogenesis of various glomerulonephritis." (PMID 35725391, 2022). "Infliximab was discontinued, and the combination of corticosteroids, tonsillectomy, and secukinumab, an IL-17A inhibitor, improved both the skin symptoms and the glomerulonephritis." (PMID 32842976, 2020). "A previous study carried out by our group showed that transgenic mice that overexpressed PP2Ac in T cells developed glomerulonephritis, which included increased production of IL-17A and IL-17F." (PMID 33597953, 2020). "Crescentic glomerulonephritis was enhanced in IL-17A−/− mice, with increased glomerular T cell accumulation and augmented TH1 responses." (PMID 25352848, 2014). "They used a mouse model of crescentic anti-GBM glomerulonephritis assessing the renal injury and immune responses in IL-17A−/− and in wild-type (WT) mice." (PMID 25352848, 2014). "By using Fcgr2b-/- mice that were also deficient in Act1, a crucial adaptor molecule downstream from the IL-17RA/IL-17RC complex, it was shown that IL-17A deletion significantly reduced inflammatory monocyte and neutrophil infiltration and thus the severity of glomerulonephritis." (PMID 32059488, 2020). "The critical role of IL-17A and TH17 cells in experimental crescentic glomerulonephritis was first shown in experimental models of glomerulonephritis, using mice with IL-23 p19, IL-17A, IL-17F, IL-17C and RORγt gene deficiency that all show impaired TH17 immune responses." (PMID 33598825, 2021). "In patients with anti-MPO glomerulonephritis, MPO-specific CD4+ T cells mediate organ damage, recognizing MPO released by NETosis as an autoantigen, conducting delayed-type hypersensitivity promoting IFN-γ and IL-17A production." (PMID 33176801, 2020). "Anti-IL17A treatment did not impact development of anti-MPO antibodies, onset of glomerulonephritis or pulmonary vasculitis." (PMID 40821760, 2025).
injury (39 papers, 2011 to 2026). Damage inflicted on the body as the direct or indirect result of an external force, with or without disruption of structural continuity. "One should be aware that IL-17A deficient mice can display a compensatory hyperproduction of IL-17 F in some experimental settings such as LPS-induced acute lung injury (Bosmann and Ward, unpublished results)." (PMID 23369364, 2012). "These novel findings demonstrate that immunosuppression via the IL-17A pathway plays a critical role in the initiation of chronic lung injuries upon sub-chronic PM exposure." (PMID 35739565, 2022). "In the mouse model of myocardial ischemia–reperfusion injury, IL-17A was mainly produced by γδ T cells, and blockade of IL-17A significantly reduced neutrophil infiltration in the heart and alleviated cardiac injury." (PMID 33981320, 2021). "Vγ4 T cells as major source of IL-17A played critical role in skin inflammation at early stage of skin injury." (PMID 29225596, 2017). "This study delineates a pathogenic IL-17A-neutrophil-NET axis that amplifies lung immunopathology in DAD, providing mechanistic insights into the interplay between immune and structural cells in acute lung injury." (PMID 40568586, 2025). "While DOXO-induced oxidative stress and NF-κB activation are well documented, our findings are the first to demonstrate that selective AURKA inhibition can simultaneously downregulate the IL-17A-driven STAT3/HIF-1α/TGF-β1/VEGF-A axis in DOXO-induced liver injury." (PMID 40872590, 2025). "There was a statistically significant positive correlation between the interleukin-17A concentrations of the multiple trauma patients at time point 24 h and the corresponding SIRS scores on day 2 with an r = 0.577 (p value = 0.0418) and on day 3 with an r = 0.5935 (p value = 0.0455)." (PMID 33931112, 2021). "Moreover, GLSO reduced IL-17A and IFN-γ expression after skin injury." (PMID 32692722, 2020).
leprosy (39 papers, 2009 to 2026). Leprosy is a chronic infectious disease affecting primarily the skin and peripheral nervous system. "In agreement with Pedia snipe data, the authors found IL-17A (rs2275913) A allele was lower than G allele (29.2% and 70.8% respectively), and AA genotype was the lowest genotype (10/60, 16.7%) in leprosy patient group." (PMID 36153175, 2022). "To validate whether enhanced IL-6R expression on CD4+ T cells is causative of elevated IL-17A response in T1R leprosy patients, we studied the effect of blocking of IL-6R and IL-23R in MLSA induced IL-17A production by PBMCs cells in-vitro." (PMID 32934336, 2020). "In this study we aimed to identify the genotypic and allelic frequencies of IL-17A G-197A (rs227593) and IL-17F A7488G (His161Arg, rs763780) gene SNPs in the context of leprosy to identify if there was any association with susceptibility to leprosy in the Mexican Mestizo population." (PMID 25431761, 2014). "The identification of Th17 cells as major inducers of antimicrobial genes in RR lesions through the expression of TNF, IFNG, and IL17A provides important new insights into the role of this T cell subset in leprosy immunopathogenesis." (PMID 40569678, 2025). "Patients with paucibacillary leprosy serum exhibited elevated levels of IL-17A and IL-1b compared to individuals with multibacillary." (PMID 38130570, 2023). "Both types of patients with reactional leprosy demonstrated a rise in IL-17A, IL-17F, and IL-22 levels." (PMID 37809252, 2023). "A gene set signature involving bacterial genes ML2388, ML2664, and host immune genes CXCL10 and IL-17A can be transcriptomic markers for reactional states in leprosy." (PMID 37051521, 2023). "In conclusion, we recommend bacterial genes ML2388, ML2664, and host immune genes CXCL10 and IL-17A as transcriptomic signatures for reactional states in leprosy." (PMID 37051521, 2023). "To determine the regulatory role of RORγt in IL-17A expression, we cultured suspensions of cells from the lesion of leprosy patients ex vivo." (PMID 36389696, 2022). "Although there were differences in production of IL-22, TNF-α and IFN-γ between lesions of TT leprosy and healthy controls, skin dermal γδ T cells mainly produced large amount of IL-17A." (PMID 36389696, 2022). "More importantly, we confirmed that γδ T cells and IL-17A secreted by these cells under the regulation of RORγt were crucial for leprosy protection in situ." (PMID 36389696, 2022). "IL-17A serum level was significantly higher in leprosy patients than in controls (p = 0.034), and in TL than LL (p = 0.017)." (PMID 36153175, 2022). "These cells were the major IL-17A–excreting cell type in the skin of leprosy patients after IL-23 stimulation and had a unique surface phenotype." (PMID 36389696, 2022). "IL-17A serum level was not affected by any personal or clinical data of the studied leprosy cases except for gender as a significantly higher serum IL-17A levels were reported in female than male leprosy patients (p = 0.007)." (PMID 36153175, 2022). "There was significant higher IL-17A serum levels in leprosy patients (4.84 ± 6.79) than the control group (2.04 ± 2.25) (p = 0.034), which was significantly higher in TL (4.52 ± 5.87) than LL (2.91 ± 1.69) (p = 0.017)." (PMID 36153175, 2022). "In summary, our present study for the first time reports that CD4+IL6R+ T cells are involved in IL-17A production in T1R leprosy patients." (PMID 32934336, 2020). "Subsequently, IL-6R and IL-23R blocking experiments showed significantly (p < 0.002) down regulated IL-17A in T1R reaction as compared to NR leprosy patients." (PMID 32934336, 2020). "Secondly, M. leprae (MLSA) antigen activates IL-6R to produce IL-17A by CD4+ T cells from T1R leprosy patients." (PMID 32934336, 2020). "On the other hand, IL-23R+IL-17A+ T cells were found to be insignificant between T1R (1.3 ± 0.6) and NR (1.0 ± 0.8) leprosy patients." (PMID 32934336, 2020).
leprosy (continued). "In conclusion, Th17 cells with intracellular IL-17A, F are increased in both types of leprosy reactions whereas CD4+IL-21+ cells were higher only in ENL reactions patients." (PMID 27035913, 2016). "Both types of reactions are associated with significant increase of Th17 cells and associated cytokines IL-17A, IL-17F, IL-21, IL-23 and chemokines CCL20, CCL22 as compared to matching stable forms of leprosy." (PMID 27035913, 2016). "We further investigated the requirement for phosphorylation of STAT3 in CCR6+ IL-17A+ cells using flowcytometry in 3 of each leprosy patients." (PMID 27035913, 2016). "We investigated the possible association with leprosy in 144 Mexican Mestizo individuals (75 leprosy patients and 69 healthy controls) who were genotyped for the IL-17A G-197A (rs227593) and IL-17F A7488G (His161Arg, rs763780) gene polymorphisms." (PMID 25431761, 2014). "At the site of the dermal lesions IL-17 was expressed at lower levels as compared to PBMC cultures and IL-17A was the more discriminatory isoform in leprosy lesions." (PMID 23936569, 2013). "A recent study on Brazilian populations indicated reduced expression of IL-17A in leprosy skin as compared to healthy subjects and attributed it to genetic differences." (PMID 23936569, 2013). "They looked for reduced RNA expression of IL-17A in leprosy patients by using ELISA and PCR." (PMID 37809252, 2023). "Moreover, our results revealed that the transcription factor RORγt was responsible for IL-17A expression in leprosy lesion." (PMID 36389696, 2022). "In conclusion, we demonstrated the role of IL-17A–producing γδ T cells in the lesion of TT leprosy." (PMID 36389696, 2022). "In leprosy patients, there was a statically significant relationship between IL-17A (rs2275913A/G) genotypes and serum IL-17A levels as the highest levels were found in IL-17A (rs2275913A/G) AG genotype carriers and the lowest levels were found in AA genotype carriers (p = 0.005)." (PMID 36153175, 2022). "Therefore, further analysis in this study, we focused on lesion of TT leprosy, as IL-17A+ γδ T cells in this group showed more significantly enrichment in lesions." (PMID 36389696, 2022). "Because proliferation of M. leprae antigen-specific Th17 cells depend on TCR engagement with high IL-6R expression and is correlated with specific IL-17A response in our study, this mechanism explains the increased IL-6R expression in T1R as compared to NR leprosy individuals in this study." (PMID 32934336, 2020). "In conclusion, we identify lack of association of IL-17A G-197A (rs227593) and IL-17F A7488G (His161Arg, rs763780) gene SNPs with susceptibility to leprosy in Mexican population." (PMID 25431761, 2014). "That the IL-17 release was also influenced by the leprosy spectrum was indicated by BT patients who showed significant increase in expression of IL-17 isoforms: IL-17A (p<0.0002), IL-17C (p<0.003), IL-17D (p<0.003) and IL-17F (p<0.0001) as compared to the multibacillary LL patients." (PMID 23936569, 2013). "Although IL-17A (rs2275913A/G) polymorphisms have a non-significant role in the genetic susceptibility to the development of leprosy, IL-17A (rs2275913A/G) GG genotype, as well as G allele, were of significant value in and linked to the progression to LL in the Egyptian population." (PMID 36153175, 2022). "Therefore, the present study confirmed the evidence of a lack of relationship between IL-17A (rs2275913A/G) gene polymorphism and leprosy susceptibility." (PMID 36153175, 2022). "Thus, dermal γδ T cells were critical IL-17A–producing cells in protection of TT leprosy." (PMID 36389696, 2022). "Also, TCRγδ+IL-17A+ cell increased in TT leprosy lesion compared with the healthy control group." (PMID 36389696, 2022). "Through blocking rIL-6 and rIL-23, IL-17A expression decreased and TGF-β expression increased, confirming the roles of these cytokines in leprosy." (PMID 37909507, 2023).
leprosy (continued). "In contrast, the expressions of NGF and NGFR were negatively correlated with the proportion of dermal IL-17A–producing γδ T cells, indicating negatively regulation of IL-17A+ γδ T cells on NGF and NGFR expression in lesion of TT leprosy." (PMID 36389696, 2022). "A rise in Th17 cells was seen in patients of both types of reactional leprosy in comparison to the non-reactional ones with identical symptoms, as demonstrated by the presence of IL-17F and IL-17A in CD4 cells." (PMID 37809252, 2023). "Studying IL-17A (rs2275913A/G) SNP showed that there was a statistically non-significant difference between leprosy patients and the control group regarding IL-17A (rs2275913A/G) genotypes (p = 0.898) and alleles distribution (p = 0.625)." (PMID 36153175, 2022). "Distinct double positive IL17A and IL17F TH17 cells induce inflammation in patients with leprosy." (PMID 32516406, 2020). "While IL-17A is produced by CD4+ Th17 cells, it is involved in neutrophilia, inflammation, tissue destruction, and repair through the control of regulatory molecules (programmed death-1/programmed death ligand-1) and is also related to reverse reaction (RR) episodes in leprosy patients." (PMID 36142557, 2022). "Dermal γδ T cells were approximately 30% IL-17A+ in TT leprosy and in LL were nearly 20%, whereas the fraction for CD4+ T cells was only about 20% in TT groups with even lower percentage in LL groups, indicating higher fraction of IL-17A+ in γδ T cells than in CD4 T cells." (PMID 36389696, 2022). "Also, they discovered that, in leprosy patients with TT form, skin lesions and peripheral blood mononuclear cell (PBMC) preparations activated with M. leprae antigen had greater expression and release of IL-17A." (PMID 36389696, 2022).
nephritis (39 papers, 2010 to 2025). Inflammation of renal tissue. "This suggests that high IL-12p40:IL-17 A ratio is a signature of SLE-associated nephritis." (PMID 39567666, 2024). "Depending on the experimental model, IL-17 cytokines IL-17A and IL-17F may exert either pathogenic or protective effects, e.g. promoting respiratory allergy or mediating protection in nephritis." (PMID 32251446, 2020). "This case highlights the potential role of dual IL-17A/F inhibition in managing refractory HS complicated by IgA vasculitis and nephritis." (PMID 41567199, 2025). "General proinflammatory and inflammatory cytokines are increased in IgA vasculitis and nephritis, such as IL-1β, IL-4, IL-6, IL-8, IL-12p70, IL-17A, TNF-α, and IFN-γ." (PMID 34299162, 2021). "Neutrophil recruitment to the kidney starts several hours after the induction of anti-GBM nephritis and its mediated by interleukin-17A (IL-17)-producing γδT cell." (PMID 30123390, 2018).